RPGRIP1L (RPGRIP1 like)
Diseases named in the same sentence as RPGRIP1L in open-access papers (continued):
Sharing a sentence is not in itself a finding about the gene and the disease.
Joubert syndrome (17 papers, 2011 to 2025). Joubert syndrome (JS) is characterized by congenital malformation of the brainstem and agenesis or hypoplasia of the cerebellar vermis leading to an abnormal respiratory pattern, nystagmus, hypotonia, ataxia, and delay in achieving motor milestones. "SLC6A2 interacts with RPGRIP1L, a ciliary protein known to cause Joubert syndrome, MKS and bipolar disorder." (PMID 32973177, 2020). "NPHP8 (RPGRIP1L) represents a particularly important component, given its dual role in both nephronophthisis and retinal ciliopathies, with mutations not only causing nephronophthisis but also contributing to Joubert syndrome and Leber congenital amaurosis." (PMID 40806500, 2025). "Joubert syndrome 7 is caused by mutations in the RPGRIP1L gene." (PMID 38013309, 2023). "For example, mutations in RPGRIP1 can cause Leber congenital amaurosis (LCA) and cone-rod dystrophy (CORD), while mutations in RPGRIP1L may cause Joubert syndrome and Meckel syndrome, etc." (PMID 31775781, 2019). "Also RPGRIP1L, mutated in Joubert syndrome with cerebellar hypoplasia, retinal dystrophy and variable cortical malformation, has disrupted alternative splicing in patients with INTS8 mutations." (PMID 28542170, 2017). "However, the proportion of RPGRIP1L mutations is the highest in our study of Joubert syndrome." (PMID 35858853, 2022). "Mutations in the RPGRIP1L gene cause Joubert syndrome (JBTS) and Meckel syndrome (MKS), two severe ciliopathies that are characterized by central nervous system malformation, cystic kidneys, polydactyly, retinal degeneration, and retinal dystrophy." (PMID 30689641, 2019). "According to previous reports, variation of RPGRIP1L gene can lead to Joubert syndrome, but the detection rate is low, only 1–2%, mostly accompanied by kidney damage." (PMID 35858853, 2022). "In humans, mutations in RPGRIP1L cause Meckel syndrome, nephronophthisis, Joubert syndrome or COACH syndrome (Joubert syndrome with congenital hepatic fibrosis)." (PMID 29650680, 2018). "Here we describe the case of a patient with clinical characteristics compatible with Joubert syndrome and a novel deleterious mutation in the RPGRIP1L gene that had not been reported in the literature before." (PMID 38013309, 2023).
Meckel syndrome (14 papers, 2010 to 2024). "Rfx3 encodes a transcription factor controlling the expression of many genes involved in ciliary assembly and function; RPGRIP1L is mutated in Joubert and Meckel Gruber Syndromes and codes for a transition zone protein." (PMID 33604340, 2021). "The ciliary gene RPGRIP1L is mutated in cerebello-oculo-renal syndrome (Joubert syndrome type B) and Meckel syndrome." (PMID 28403078, 2017). "Among them, the RPGRIP1l: c.1351-11A > G had been reported in a Chinese family diagnosed Meckel syndrome." (PMID 37547106, 2023). "For example, RPGR exists in complex with NPHP5 (or IQ domain containing calmodulin binding protein [IQCB1]; SLSN), centrosomal protein of 290 kDa (CEP290)/NPHP6 (Leber congenital amaurosis, SLSN, JBTS), and NPHP8/RPGRIP1-like (RPGRIP1L; mutated in JBTS and Meckel-Gruber syndrome) in the retina." (PMID 20664800, 2010). "We find that the TZ protein MKS-5 (Rpgrip1/Rpgrip1L orthologue) forms the foundation for two different assembly pathways involving two distinct modules: Nephronophthisis (NPHP) and Meckel syndrome (MKS)." (PMID 26982032, 2016). "The other splicing variation is RPGRIP1l: c.1351-11A > G, which has only been found in a Chinese family with Meckel syndrome, but never been reported about this locus and the nearby regions related to JBTS." (PMID 37547106, 2023).
nephronophthisis (9 papers, 2011 to 2025). Progressive tubulointerstitial injury, inherited in an autosomal recessive pattern, caused by mutations in genes involved in ciliary function, which may result in an end stage renal failure. "RPGRIP1L gene is also known as NPHP8 gene which is one of genes cause nephronophthisis (NPHP, MIM 256100)." (PMID 35858853, 2022). "The RPGRIP1L gene, also known as the NPHP8 gene, which is one of the genes that causes nephronophthisis (NPHP, MIM 256100), deserves special mention." (PMID 37993833, 2023). "Seventeen patients carried heterozygous variants in at least one of 13 other genes (including NPHP4, RPGRIP1L, TMEM216, CC2D2A, and MKS1) implicated in nephronophthisis or associated syndromes, suggesting modified genetic activity." (PMID 37628633, 2023). "In patients with syndromic nephronophthisis caused by several genes (including NPHP3, IQCB1, CEP290, and MKS1), an additional heterozygous variant in RPGRIP1L is associated with retinitis pigmentosa." (PMID 37628633, 2023). "Common variants are associated with elevated creatine in association studies;In patients with syndromic nephronophthisis caused by several genes (including NPHP3, IQCB1, CEP290, and MKS1), an additional heterozygous variant in RPGRIP1L is associated with retinitis pigmentosa." (PMID 37628633, 2023).
retinal degeneration (8 papers, 2010 to 2025). Degeneration of the retina. "This hypothesis is supported by our previous report that a hypomorphic allele of RPGRIP1L, A229T, although affects protein function in zebrafish rescue assays, is frequently associated with retinal degeneration in patients with founder mutation in a different gene." (PMID 21738648, 2011). "The major phenotypes in our patients were consistent with those in previous reports indicating that the CEP290 mutation is correlated with retinal degeneration and kidney disease, TMEM67 is correlated with liver disease, and RPGRIP1L is correlated with kidney disease." (PMID 33432080, 2021).
Joubert syndrome 7 (4 papers, 2018 to 2023). Any Joubert syndrome in which the cause of the disease is a mutation in the RPGRIP1L gene. "Defects of RPGRIP1L can cause of Joubert syndrome type 7 and Meckel syndrome type 550,51." (PMID 29472535, 2018).
Intellectual disability (3 papers, 2021 to 2023). "Previous reports have shown that RPGRIP1L gene mutation is associated with cerebellar vermis hypoplasia, intellectual disability/development delay, NPHP, and ocular motor apraxia (OMA) in JS patients." (PMID 37993833, 2023).
Kidney Cyst (3 papers, 2018 to 2022). Abnormal fluid filled sac within the kidney, either acquired or congenital. "Another TZ protein, RPGRIP1L is also mutated in Merkel Syndrome (MKS) which is characterized by kidney cysts." (PMID 33488951, 2020).
cyst (2 papers, 2015 to 2025). A sac-like closed membranous structure that may be empty or contain fluid or amorphous material. "RPGRIP1L−/− mutant organoids treated with 5 μM hydroxyfasudil and 2.5 μM fasudil had significantly fewer cysts (p = 0.01059 and p = 0.03711, respectively), whereas cyst number remained unchanged for control organoids treated with ROCK inhibitors or 8-Br-cAMP." (PMID 40253509, 2025).
developmental delay (2 papers, 2013 to 2021). "RPGRIP1L and RPGRIP1 are known to interact with the NPHP4 C2 domain, and mutations in both can cause developmental delay by interfering with neuronal development." (PMID 34722527, 2021).
Gruber syndrome (2 papers, 2020 to 2024). "The TZ module proteins (Meckel Gruber syndrome [MKS]/Nephronophtysis [NPHP]/Centrosomal protein of 290 kDa [CEP290]/Retinitis pigmentosa GTPase regulator-Interacting Protein 1-Like Protein [RPGRIP1L]) are known to cooperate to establish TZ formation and function." (PMID 32163404, 2020).
hepatocellular carcinoma (2 papers, 2016 to 2018). A malignant tumor that arises from hepatocytes. "It was previously reported that the ciliary gene RPGRIP1L might serve as a tumor suppressor gene because RPGRIP1L was downregulated in human hepatocellular carcinoma." (PMID 27293550, 2016). "Since knockdown of RPGRIP1L led to an increased amount of MAD2, the function of RPGRIP1L as a controller of ciliary proteasome activity could be of great importance in the prevention of human hepatocellular carcinoma formation." (PMID 27293550, 2016).
retinitis pigmentosa (2 papers, 2015 to 2023). Retinitis pigmentosa (RP) is an inherited retinal dystrophy leading to progressive loss of the photoreceptors and retinal pigment epithelium and resulting in blindness usually after several decades. "In patients with a variety of syndromic ciliopathies attributed to variants in NPHP3, IQCB1, CEP290, and MKS1, a common RPGRIP1L variant (p.Arg229Thr) (present in over 8% of South Asians and 3% of other populations) is significantly enriched in patients who also have retinitis pigmentosa." (PMID 37628633, 2023). "Mutations in SPTBN5 and RPGRIP1L cause retinitis pigmentosa." (PMID 26083354, 2015).
scoliosis (2 papers, 2022 to 2024). A congenital or acquired spinal deformity characterized by lateral curvature of the spine. "Here, we dissected the mechanisms of scoliosis onset in a zebrafish mutant for the rpgrip1l gene encoding a ciliary transition zone protein." (PMID 39388365, 2024). "In this paper, we dissect the mechanisms of scoliosis appearance in a novel deletion allele of the zebrafish TZ rpgrip1l gene." (PMID 39388365, 2024). "Still, as scoliosis onset in rpgrip1l mutant is asynchronous from 5 to 12 weeks, MCC loss at SCO exit could contribute to defective RF polymerization." (PMID 39388365, 2024). "Thus, the cascade of events uncovered in the rpgrip1l mutant sheds a new light on the origin of zebrafish scoliosis caused by ciliary transition zone defects." (PMID 39388365, 2024). "Our data show that rpgrip1l deficiency in zebrafish affects cilia maintenance differentially depending on the CNS territory and the developmental stage, raising the question of which ciliated cells are responsible for RF loss and scoliosis initiation in this mutant." (PMID 39388365, 2024). "Transcriptomic and proteomic studies identified neuroinflammation associated with increased Annexin levels as a potential mechanism of scoliosis development in rpgrip1l juveniles." (PMID 39388365, 2024). "rpgrip1l-/- juvenile fish develop scoliosis, which is rescued by RPGRIP1L expression in foxj1a-positive cells." (PMID 39388365, 2024). "(M) Graph representing the percentage of GFAP-positive cells among the total number of SCO cells in control (n=4), straight rpgrip1l-/- (n=4), and scoliotic rpgrip1l-/- (n=3) fish at scoliosis onset (N=1)." (PMID 39388365, 2024). "NACET treatment showed that increased astrogliosis and inflammation participated in the penetrance and severity of scoliosis in rpgrip1l-/- fish." (PMID 39388365, 2024). "We then took advantage of the asynchrony in scoliosis onset to correlate, at a given stage, cilia defects at different levels of the CNS cavities with the spine curvature status (straight or curved) of rpgrip1l-/- juveniles." (PMID 39388365, 2024). "(A) Kinetics of scoliosis development in rpgrip1l+/- incrosses in the presence (n=150 fish) or absence (n=174 fish) of NACET treatment (1.5 mM) from 4 to 12 weeks (N=1)." (PMID 39388365, 2024). "In the case of the rpgrip1l mutant, we temporally uncorrelated fChP cilia defects from scoliosis onset." (PMID 39388365, 2024). "Anxa2 and GFAP upregulation and increased number of LCP1-positive cells around CNS ventricles of rpgrip1l-/- juvenile fish at scoliosis onset." (PMID 39388365, 2024). "rpgrip1l mutant fish developed scoliosis with near-total penetrance but asynchronous onset in juveniles." (PMID 39388365, 2024). "Transcriptome analysis of the brain and trunk at scoliosis onset in rpgrip1l-/- fish compared to control siblings revealed increased expression of urp1/2, foxj1a and its target genes, as well as genes linked to immune response." (PMID 39388365, 2024). "NACET treatment reduces scoliosis penetrance and severity in rpgrip1l-/- and decreases astrogliosis and LCP1 + cell number at SCO level." (PMID 39388365, 2024). "We tested if introducing by transgenesis a tagged human RPGRIP1L protein under the control of the col2a1a or foxj1a enhancers would reduce scoliosis penetrance and severity." (PMID 39388365, 2024). "In this paper, we dissected the mechanisms of scoliosis appearance in a zebrafish mutant for the TZ gene rpgrip1l, taking advantage of its asynchronous onset to decipher the chronology of events leading to spine torsion." (PMID 39388365, 2024). "(B, C) Graph showing the time course of scoliosis appearance (B) in rpgrip1l-/+ incrosses (total 4 clutches, 252 fish) and scoliosis penetrance (C) in adults." (PMID 39388365, 2024).
scoliosis (continued). "Overall, rpgrip1l-/- mutants at scoliosis onset present deregulated pathways in common with other scoliotic models such as activation of immune response genes, but also specific deregulated pathways such a marked activation of the Foxj1a ciliary motility program and an increase of Annexin levels." (PMID 39388365, 2024). "rpgrip1l-/- animals developed scoliosis during juvenile stages." (PMID 39388365, 2024). "To get further insight into the early mechanisms driving spine curvature in rpgrip1l mutants, we obtained the transcriptome of the brain and dorsal trunk of 7 rpgrip1l-/- juveniles at scoliosis onset (6 tail-up and 1 straight 5 wpf juveniles) and 5 control siblings (2 rgprip1l+/+ and 3 rgprip1l+/-)." (PMID 39388365, 2024). "Our data suggest that astrogliosis and neuro-inflammation could play a role in triggering scoliosis in rpgrip1l mutants." (PMID 39388365, 2024). "Thus, our study uncovers a strict temporal correlation between the loss of MCC at posterior SCO level, impaired RF polymerization and scoliosis onset in rpgrip1l-/- juvenile fish." (PMID 39388365, 2024). "Finally, our observation of widespread astrogliosis in two TZ gene mutants, rpgrip1l and cep290, suggests that it could represent a general mechanism involved in scoliosis downstream of cilia dysfunction." (PMID 39388365, 2024). "As scoliosis onset is asynchronous in rpgrip1l-/-, heterogenous GFAP staining among straight mutant fish may support an early role of astrogliosis at SCO and RhV levels in scoliosis onset." (PMID 39388365, 2024). "No beneficial effect on scoliosis penetrance or severity was observed, indicating that increased urp1/2 expression level does not significantly contribute to axis curvature in rpgrip1l-/- fish." (PMID 39388365, 2024). "Surprisingly, scoliotic rpgrip1l-/- fish showed similar LCP1+ cell number as control fish in the tectum, suggesting a transient increase of macrophage/microglia activation preceding scoliosis." (PMID 39388365, 2024). "The Foxj1a:5XMycRPGRIP1L transgene was sufficient to fully suppress scoliosis in rpgrip1l-/- fish: none of the transgenic rpgrip1l-/- fish became scoliotic while virtually all the non-transgenic rpgrip1l-/- siblings did." (PMID 39388365, 2024). "In contrast, RPGRIP1L expression triggered by the col2a1a promoter did not have any beneficial effect on scoliosis penetrance." (PMID 39388365, 2024). "(I) Table presenting the number and phenotype of rpgrip1l-/- fish generated for both rescue experiments by stable transgenesis (J) Graph representing scoliosis penetrance in transgenic and non-transgenic rpgrip1l-/- siblings." (PMID 39388365, 2024). "Thus, the ciliary rpgrip1l-/- mutant shows almost totally penetrant, late-onset juvenile scoliosis without vertebral anomalies, making it a valuable model for studying the etiology of human idiopathic scoliosis." (PMID 39388365, 2024). "Thus, lowering global Urp1/2 expression level in rpgrip1l mutants did not have any beneficial effect on the axis curvature phenotype, ruling out altered urp1/2 signaling as a main driver of scoliosis in rpgrip1l mutants." (PMID 39388365, 2024).
bipolar disorder (1 paper, 2024). A disorder of the brain that causes unusual shifts in mood, energy, activity levels and the ability to carry out day-to-day tasks. "In line with this background, a post-mortem study on 7 patients with schizophrenia, 4 with bipolar disorder, and 79 controls showed variation in the levels of two transcripts of the RPGRIP1L gene among the groups, possibly correlated with the genotypes of rs8050354 and rs7203525." (PMID 38920990, 2024).
breast carcinoma (1 paper, 2025). "Additionally, high RPGRIP1L expression was linked to elevated expression of immune checkpoint Programmed Death Ligand 1(PD-L1) in human breast cancer samples." (PMID 41469586, 2025). "Through further analysis, we identified a core set of GIMGs and pinpointed RPGRIP1L as a critical driver of genomic instability in breast cancer." (PMID 41469586, 2025). "Collectively, these findings highlight RPGRIP1L as a key genomic instability-maintaining gene in human breast cancer, offering critical insights into the molecular mechanisms underlying disease progression." (PMID 41469586, 2025). "Notably, RPGRIP1L expression was significantly upregulated in breast cancer tissues and strongly correlated with poor patient prognosis." (PMID 41469586, 2025). "Furthermore, targeting RPGRIP1L may represent a promising therapeutic strategy for breast cancer." (PMID 41469586, 2025).
clubfoot (1 paper, 2016). The most common congenital deformation of the foot, occurring in 1 of 1,000 live births. "Patient # 15 with MTS had congenital clubfoot, which was occasionally reported in JBTS, namely in a 4-year-old girl with a homozygous frameshift mutation in the RPGRIP1L gene." (PMID 27473762, 2016).
Encephalocele (1 paper, 2022). A neural tube defect characterized by sac-like protrusions of the brain and the membranes that cover it through openings in the skull. "Mutations in RPGRIP1L may cause a wide range of symptoms that involve many organs, including retinal, renal, hepatic, and oculorenal symptoms, polydactyly, and encephalocele." (PMID 36468023, 2022).
end stage renal failure (1 paper, 2022). "Three patients with RPGRIP1L gene and NPHP1 gene mutation all had end stage renal failure, suggesting that RPGRIP1L gene and NPHP1 gene mutation may be related to kidney involvement especially end stage kidney disease." (PMID 35858853, 2022).
hearing loss (1 paper, 2020). "An additional five genes have not previously been associated with human hearing loss but are known to cause hearing loss or cochlear development when mutated in mice: SYNJ2, RPGRIP1L, BAIAP2L2, TUB, and RBL2." (PMID 32986727, 2020).
neuroma (1 paper, 2022). A tumor that grows from a nerve or is composed of nerve cells and nerve fibers. "Using the provided data as reference enabled us to objectively diagnose CN abnormalities, such as abnormal formation of CN3 (Col4a2), neuroma of the motor portion of CN5 (Arid1b), thinning of CN7 (Rpgrip1l) and abnormal topology of CN12 (Cc2d2a)." (PMID 36438572, 2022).
pancreatic adenocarcinoma (1 paper, 2021). "mRNA expression analysis using The Cancer Genome Atlas database revealed that RPGRIP1L was highly expressed in several cancer types, especially in pancreatic adenocarcinoma, and correlated with patient survival and sensitivity to paclitaxel, probably through the TGF-β signaling pathway." (PMID 33597970, 2021).
polycystic kidneys (1 paper, 2018). "Furthermore, while Rpgrip1nmf247/nmf247 and Rpgrip1l+/− mouse embryos do not show any defects, their combined mutations induce polycystic kidneys in Rpgrip1l+/−; Rpgrip1nmf247/nmf247 embryos demonstrating a functional synergy of Rpgrip1l and Rpgrip1 in renal development." (PMID 29650680, 2018).
pulmonary embolism (1 paper, 2018). The obstruction of the pulmonary artery or one of its branches by an embolus, sometimes associated with infarction of the lung. "Rs146925098 on RPGRIP1 like (RPGRIP1L) was found in one case with pulmonary embolism (SN3230)." (PMID 29368655, 2018).
Senior-Loken syndrome (1 paper, 2011). Senior-Loken syndrome (SLSN) is a very rare autosomal recessive oculo-renal disease characterized by the association of nephronophthisis (NPHP), a chronic kidney disease, with retinal dystrophy. "The more C-terminal C2 domain of RPGRIP1L is responsible for binding to nephrocystin-4, and mutations in NPHP4 which cause Senior Loken Syndrome disrupt this interaction with RPGRIP1L." (PMID 21857984, 2011).